CXCL10 (C-X-C motif chemokine ligand 10)
Diseases named in the same sentence as CXCL10 in open-access papers (continued):
Sharing a sentence is not in itself a finding about the gene and the disease.
ovarian carcinoma (continued). "The comprehensive evaluation of CXCL10 in TME may help to expand our understanding of chemokine-related TME immune characteristics and obtain more effective immunotherapy strategies in ovarian cancer." (PMID 34386037, 2021). "In this study, based on visual inspection curves of estimated survival dependent on CXCL10 and CXCL9 expression, we integrated multiple datasets with gene expression, which contained 1,673 cases in total to explore ovarian cancer TME immunological characteristics from immune signature gene sets." (PMID 34386037, 2021). "For instance, treatment of ovarian cancer cells with epigenetic modifiers reversed the EZH2 and DNMT1 suppression of expression of the CXCR3 ligands, CXCL9, and CXCL10, resulting in T cell influx into the tumor and improved response to T cell transfer and anti-PD-L1 blockade therapy." (PMID 30873179, 2019). "In contrast, high CXCL9, CXCL10, and CXCL11 expression in the TME of patients with colorectal, oesophageal, non-small cell lung (NSCL) and ovarian cancer is an indicator of improved overall survival, while it is a poor prognostic marker in patients with localized clear-cell RCC." (PMID 30319622, 2018). "Additionally, the combination increased CXCL10 levels in both cell culture and ascites fluid, promoting immune cell recruitment and correlating with reduced tumor burden in models like ID8-VEGF-Defensin, which mirrors human ovarian cancer dynamics." (PMID 41029427, 2025). "Consistent with the previous studies, CXCL10-positive tumors had higher antigen processing, antitumor immune response, and TIL accumulation, thereby suggesting that CXCL10 expression is a predictive biomarker to evaluate immune cell infiltration in ovarian cancer TME." (PMID 34386037, 2021). "In ovarian cancer cell lines, inhibition of EZH2 using DZNep (inhibitor of SAM dependent enzymes), EPZ6438 and GSK126 (selective inhibitor of EZH2) and DNMT (azacytadine) synergistically increase IFN-γ responsiveness, and CXCL9 and CXCL10 expression, while shrinking tumor size." (PMID 34163486, 2021). "Similarly, the evolving ovarian cancer metastatic tumors are metabolically reprogrammed by CAFs through the secretion of C-C Motif Chemokine Ligand 5 (CCL5), C-X-C motif chemokine ligand 10 (CXCL10), and IL-6 to utilize glycogen." (PMID 30380628, 2018). "who incubated primary ovarian cancer cells with 5-aza-2′-deoxycytidine, a deoxy derivative of 5-Aza, which resulted in the hypomethylation of an STAT-1 binding site upstream of the promoter region and an exacerbated release of CXCL10 following IFN-γ stimulation." (PMID 29223680, 2018). "Using female healthy donors with no history of ovarian cancer, we were also able to detect levels of CCL2, CCL4, CCL5, CXCL10 and CXCL12." (PMID 41424784, 2025). "To date, the comprehensive landscape of CXCL10-related immune cell infiltration and TME characteristics in ovarian cancer have not been elucidated." (PMID 34386037, 2021).
lung carcinoma (75 papers, 2011 to 2025). "MEKis upregulated CXCL10 expression after RT in KRAS-mutated lung cancer, with CXCL10 serving as a pivotal factor in immune activation." (PMID 41368644, 2025). "The chemokines IL-8 and IP-10 (CXCL10) have been identified as biomarkers that improved the prediction of lung cancer incidence in combination with lung cancer risk models." (PMID 37849764, 2023). "Overall, enforcing the viral entry and cytokine storm, the over-expressed ACE2 and CXCL10 become major factors of the higher susceptibility and fatality rate of lung cancer patients towards COVID-19 infection." (PMID 33585826, 2021). "The recent spatial transcriptomic analysis of human lung cancer patients indicates that spatially organized ‘immunity hubs’ consisting of stem-like IFNγ+ T cells in residence with myeloid cells in a CXCL10/11-CXCR3 dependent manner are associated with positive response to anti-PD-1 therapy." (PMID 38786066, 2024). "Therefore, we performed a functional characterization of ACE2 and CXCL10 in lung cancer by analyzing the mutations and copy number alterations in their protein sequence based on 21 lung cancer studies." (PMID 33585826, 2021). "Therefore, based on this systemic analysis, we can pinpoint that ACE2 and CXCL10 are possible biomarkers whose higher expressions are responsible for the greater susceptibility and fatality of lung cancer patients towards the COVID-19 infection." (PMID 33585826, 2021). "The activation of TLR7–IFN signaling in lung cancer cells leads to an increase in the secretion of chemokine CXCL10, which contributes to immune cell infiltration." (PMID 40727252, 2025). "Cxcl9/Cxcl10-engineered dendritic cells were reported to promote T cell activation and enhance immunotherapy in lung cancer, highlighting the critical role of DCs in cancer." (PMID 40282557, 2025). "The results indicated that IFNα/γ-downstream IRF1 and STAT1 both potentially mediated PD-L1 and CXCL10 expression in lung cancer." (PMID 38953994, 2024). "A recent elegant spatial transcriptomic analysis of human lung cancer revealed spatially organized ‘immunity hubs’ where stem-like T cells reside with myeloid cells through CXCL10/11–CXCR3 axis." (PMID 38786066, 2024). "Inhibition of lysine-specific demethylase 4C (KDM4C) augments CD8+ T cell-mediated antitumor immunity in lung carcinoma by activating CXCL10 transcription." (PMID 39346534, 2024). "In summary, we demonstrated that TPE induces Arg-1 M2 polarization of MФ via CXCL9/CXCL10, which promotes the progression of lung cancer via autophagy/E-cadherin signaling." (PMID 38720340, 2024). "CXCL10 is a chemokine that is frequently elevated during EGFR-TKI treatment in the tumor microenvironment of lung cancer." (PMID 37484803, 2023). "Meanwhile, we notice that CXCL10 is also low expressed in the PBMCs of patients with lung cancer compared to healthy volunteers and in a patient’s PBMCs co-incubated with A549 cells compared to a healthy volunteer." (PMID 36688994, 2023). "A prospective study of 32 lung cancer patients treated with ICI showed that patients with high baseline plasma CXCL10 concentration experienced significantly shorter PFS than patients with low CXCL10 concentration." (PMID 36831044, 2023). "We further demonstrated that the CXCR3 ligand CXCL10 decreased in the PBMCs of patients with lung cancer compared to healthy volunteers." (PMID 36688994, 2023). "In conclusion, we validated that RT suppressed lung cancer and overexpress PD-L1, CXCL10, and ICAM-1, which exhibited different roles in regulating CD8+ T cell activity." (PMID 36688994, 2023). "We demonstrate that a CXCL10/CXCR3 pathway is activated in EGFR-mutant lung cancer cells when cocultured with activated PBMCs and exposed to EGFR-TKI treatment." (PMID 36612121, 2022). "CXCL10 is a cytokine that is elevated during EGFR-TKI treatment in the tumor microenvironment of lung cancer." (PMID 36612121, 2022).
lung carcinoma (continued). "On the other hand, CCR6+ILC3s (Lti cells) have an anti-tumoral role in chemotherapy treated lung cancer by secreting CXCL10, which is a chemoattractant of CD4+ and CD8+ T cells." (PMID 36341381, 2022). "In this study, we found that KDM4C inhibition enhanced the transcriptional activity of CXCL10 by increasing the concentration of H3K36me3 at its promoter region in lung cancer." (PMID 35121645, 2022). "Our findings indicate that autocrine and paracrine activations of the CXCL10/CXCR3 pathway contribute to early EGFR-TKI resistance in EGFR-mutant lung cancer." (PMID 36612121, 2022). "The aberrantly high expression of KDM4C in lung cancer inhibits CXCL10 transcription by reducing the enrichment of activated histone H3K36me3 at the CXCL10 promoter region, thus decreasing the infiltration and activation of CD8+ T cells." (PMID 35121645, 2022). "This suggests that the increase in CXCL10 in the tumor microenvironment during EGFR-TKI treatment paradoxically increases oncogenic pathway activity in EGFR-mutant lung cancer through Src-NF-κB-HIF-1α signaling." (PMID 36612121, 2022). "More importantly, using ChIP-PCR, we revealed that H3K36me3 binding at the promoter region of CXCL10 was increased considerably after KDM4C inhibition, indicating that KDM4C directly regulates the transcriptional level of the CXCL10 gene in lung cancer." (PMID 35121645, 2022). "Recently, CXCL10 levels were found to be elevated in EGFR-mutant lung cancer immediately after EGFR-TKI treatment." (PMID 36612121, 2022). "Together, our results suggest that there is crosstalk among cytokines, tumor cells, and the immune microenvironment, and they highlight the paradoxical oncogenic properties of CXCL10 in EGFR-mutant lung cancer during EGFR-TKI therapy." (PMID 36612121, 2022). "CXCL10 is secreted primarily by monocytes, but EGFR-mutant lung cancer cells have also been shown to produce CXCL10 in response to IFN-γ." (PMID 36612121, 2022). "Next, we went through a similar type of analysis for interpreting the genetic alterations in the CXCL10 mRNA regarding lung cancer." (PMID 33585826, 2021). "Results of our current comprehensive study of cytokines did reveal that the transfection of miR‐1 into three different human lung carcinoma cell lines harboring EGFR mutations significantly decreased the expression of CCL5, CXCL10, IL‐6, IL‐8, and TNF‐α." (PMID 33305905, 2021). "Overall, the functional characterization of ACE2 and CXCL10 by using multiple lung cancer studies provides some of the vital evidence of their intimate relationship with lung cancer development." (PMID 33585826, 2021). "We then identified the functional significance of ACE2 and CXCL10 in lung cancer development by determining the genetic alteration frequency in their amino acid sequences using the cBioPortal web portal." (PMID 33585826, 2021). "Our results support the notion that CXCL9 and CXCL10 are also critical in the context of lung cancer immunotherapy." (PMID 34206510, 2021). "To evaluate the probable reasons behind the excessive susceptibility and fatality of lung cancer patients to COVID-19 infection, we targeted the two most crucial agents, Angiotensin-converting enzyme 2 (ACE2) and C-X-C motif 10 (CXCL10)." (PMID 33585826, 2021). "We then analyze genetic alteration frequency in the CXCL10 mRNA distinct numbers of lung cancer studies." (PMID 33585826, 2021). "At the early stage of our study, we showed overexpression of CXCL10 in lung cancer and by doing the functional analysis of CXCL10 we confirmed its association with immune response." (PMID 33585826, 2021). "CXCL10 expression was found at an elevated level in both LUAD and LUSC (3e-h) which also indicates CXCL10’s involvement in lung carcinoma and the event of cytokine storm and subsequent disease fatality." (PMID 33585826, 2021).
lung carcinoma (continued). "Here, we found that ACE2 and CXCL10 along with their commonly co-expressed genes are involved respectively in the binding activity and immune responses in case of lung cancer and COVID-19 infection." (PMID 33585826, 2021). "For this, we treated A549 lung cancer cells with TNFα, IL1β, E. coli lipopolysaccharide (LPS), as well as IFNγ, and assessed secretion of the cytokines CXCL10, IL6 and IL8." (PMID 26030458, 2015). "PBMC gene expression of CCL3, IL8 and IL1β was higher in lung cancer patients compared to the same patients at each of four sequential timepoints after removal of their tumors, while CXCL10 and IL2Rα were essentially unchanged." (PMID 23762239, 2013). "In contrast, although statistically significant, IL2Rα expression was only 2 fold higher in the lung cancer patients, while CXCL10 expression was essentially unchanged." (PMID 23762239, 2013). "Additionally, elevated CXCL10 expression was observed in two human KRAS-mutant lung cancer cell lines, A549 and H23, in the combination group, similar to that in LLC." (PMID 41368644, 2025). "Moreover, we validated that PBMCs in a patient with lung cancer secreted less CXCL10 levels compared to healthy PBMCs in co-cultured with A549 for 24 h." (PMID 36688994, 2023). "Moreover, non-CD8+ PBMCs, containing NKs, macrophages, DCs, and CD4+ T cells, exhibited lower A549-stimulated CXCL10 expression in a patient with lung cancer compared to a healthy volunteer after co-cultured with A549 for 24 h." (PMID 36688994, 2023). "CXCL10 and CCL5 overexpression is associated with the presence of CD8+ T cells in lung cancer." (PMID 37937640, 2023). "Importantly, elevated CXCL10/CXCR3 signaling was recapitulated in a transgenic lung cancer mouse model." (PMID 36612121, 2022). "To test this hypothesis, we first targeted KDM4C genetically or pharmacologically in multiple human lung cancer cell lines and Lewis cells and detected a significant increase in the protein expression of CXCL10." (PMID 35121645, 2022). "Next, we further explored autocrine CXCL10 expression in EGFR-mutant lung cancer cell lines." (PMID 36612121, 2022). "CXCL10 and CXCL11 may also be useful diagnostic biomarkers in early-stage NSCLC, while CXCL8 levels may be a useful predictor of future lung cancer risk." (PMID 36164329, 2022). "Next, we explored whether EGFR-mutant lung cancer cells could secrete CXCL10 when cocultured with activated PBMCs." (PMID 36612121, 2022). "Plasma cytokines IL-18 and CXCL10 could indicate the anti-PD-1/PD-L1 treatment response in lung cancer patients and play an important role in selecting patients benefiting from PD-1/PD-L1 inhibitors." (PMID 35468838, 2022). "The in vivo production of the T cell tumor trafficking chemokine C-X-C motif chemokine ligand 10 (CXCL10) increased in murine lung cancer cells accompanied by retarded tumor growth with anti-PD-L1-IFN-α compared to parental anti-PD-L1 and a non-specific immunocytokine." (PMID 33803078, 2021). "Similarly, treatment of KRAS mutant lung cancer with MAPK pathway inhibitors induced IFN-regulated genes including CXCL10 and TNF48." (PMID 34001994, 2021). "However, the key findings of this research revealed some of the strong evidences confirming the direct interconnection of ACE2 and CXCL10 with lung cancer development." (PMID 33585826, 2021). "•The expression of ACE2 and CXCL10 is upregulated in lung cancer." (PMID 33585826, 2021). "In addition, CXCL9 and CXCL10 decreased in a patient’s nonCD8+ PBMCs but CXCL9 concentration increased in the sera of patients with lung cancer." (PMID 34680466, 2021). "It is thus possible that CXCL10 in the bone stroma may upregulate CXCR3 production in lung cancer cells, which in turn became more attracted to the bone." (PMID 33262947, 2020).
lung carcinoma (continued). "Similarly, the two cytokines (proteins) which were found at the lowest levels prior to stage I lung cancer resection (CXCL10 and soluble IL2Rα) were both corroborated by the PBMC gene expression data from the microarray database." (PMID 23762239, 2013). "Our study demonstrates that CXCL10 may mediate early NF-κB activation in EGFR-mutant lung cancer." (PMID 36612121, 2022). "Thus, we hypothesize that CXCL10/CXCR3/Src activation may mediate an oncogenic signaling pathway in EGFR-mutant lung cancer cell lines." (PMID 36612121, 2022). "Interestingly, comparing to the MDMs from HCs, some cases of lung cancer patients’ MDMs showed MPE-Mφ-like patterns on elevating expression levels of CXCL10, CCL18, and MRC1, may indicate the local and systemic effects of the tumor microenvironment." (PMID 33175182, 2021). "Additionally, CCL20 and CXCL10 play major roles in the growth, migration and metastatic capabilities of lung cancer cells and were shown to decrease immunogenicity against cancer cells through recruitment of inflammatory immune cells, leading to decreased patient survival." (PMID 31001473, 2019). "In a mouse lung cancer model, cisplatin elevated tumor IL-1β and CCL20 levels, recruiting and activating ILC3s to produce CXCL10 and bolster antitumor immunity." (PMID 40963622, 2025). "In lung cancer models, CCR6+ ILC3s producing CXCL10 attracted CXCR3+ immune cells—NK cells, T cells, DCs, and monocytes—slowing tumor progression." (PMID 40963622, 2025). "In a lung cancer model, radiation has been shown to enhance CXCR3+ T cell activation in an IFNγ-dependent manner, via CXCL10 and ICAM-1." (PMID 38786066, 2024). "Our results emphasize that elevated EPI promotes Ccl5 and Cxcl10 recruitment of CD8+ T cells to the tumor site, thereby inhibiting tumor progression in an exercise-induced lung cancer model." (PMID 38622609, 2024). "Previous research has shown that inhibiting KDM4C induces the transcription of Cxcl10, enhancing CD8+ T cell-mediated antitumor immune responses in lung cancer." (PMID 38622609, 2024). "We further demonstrated that CXCR3 and CXCL10 decreased in the CD8+ T cells and nonCD8+ PBMCs, respectively, in the patients with lung cancer that expressed lower reactivation as co-cultured with A549 cells." (PMID 36688994, 2023). "Based on the observation that RT induces PD-L1, CXCL10, and ICAM-1 at the same time, RT combined with anti-PD-1 immunotherapy is suggested in clinical practice for patients with lung cancer." (PMID 36688994, 2023). "In the lung carcinoma syngeneic model, we confirmed that RORγt agonist treatment increased intratumoral CD8+ T cells and MoDCs through the promotion of CXCL10 as well as promotion of Type 17 T cell migration via upregulation of CCL20 and CCR6 expression." (PMID 35459193, 2022). "MPE-Mφ showed relatively higher expression levels of M1 (IL-1β, IL-6, and CXCL10), M2 (CCL18 and IL-10), and pan-macrophage markers (CSF1 and PTPRC) compared to MDMs from lung cancer patients or HCs." (PMID 33175182, 2021). "Then, we further confirmed that ICT treatment increased CXCL9 and CXCL10 secretion in the mouse LLC and the human H1975 lung cancer cell lines by RT-PCR." (PMID 33460401, 2021). "To evaluate the functional significance of ACE2 and CXCL10 in lung cancer development, we generated data representing multiple genetic alterations in ACE2 and CXCL10 mRNA using the cBioPortal database." (PMID 33585826, 2021). "Here, we evaluated the clinical implications and prognostic significance of IFN-γ-inducible chemokines by measuring levels of CXCL9, CXCL10, and CXCL11 and their inducer IFN-γ in the peripheral blood of patients with lung cancer." (PMID 34501934, 2021). "The serum levels of CXCL9, CXCL10, and CXCL 11 were significantly correlated with one another in all lung cancer and NSCLC patients, but the degree of correlation was relatively weak." (PMID 34501934, 2021).